SLC6A4 (solute carrier family 6 member 4)
Diseases named in the same sentence as SLC6A4 in open-access papers (continued):
Sharing a sentence is not in itself a finding about the gene and the disease.
depression (continued). "In our study, TLE patients that showed history of depression also showed lower levels of methylation in BDNF or SLC6A4 genes." (PMID 34912196, 2021). "For clinical depression state assessment in the independent test cohort across all subjects, SLC6A4, increased in expression in low mood, had an AUC of 61% (p = 1.1E−02) if measured cross-sectionally, and AUC of 66% (p = 1.78E−02) if measured longitudinally." (PMID 33828235, 2021). "SLC6A4 (5-HTTLPR + rs25531) locus influenced the severity of symptoms of depression and personal anxiety in patients." (PMID 34199792, 2021). "SLC6A4 methylation was found to be positively correlated with stress and depression, and possessed the potential for the diagnosis and treatment of major depression." (PMID 34925022, 2021). "Basing on previous findings, we also investigated possible SLC6A4 methylation × sex × 5-HTTLPR interactions in the investigation of depression onset." (PMID 33765975, 2021). "We observed a significant effect of SLC6A4 5-HTTLPR+rs25531 on depression symptoms (p = 0.044) and personal anxiety (p = 0.029)." (PMID 34199792, 2021). "Methylation of the SLC6A4 promoter region has been previously investigated in the peripheral blood of individuals with major depressive disorder, children with childhood physical aggression and ADHD and in the saliva of paediatric OCD." (PMID 33445578, 2021). "Blood SLC6A4 methylation status and SI based on the suicide item of the Montgomery–Åsberg Depression Rating Scale were assessed in 278 patients at 2 weeks after stroke." (PMID 33526821, 2021). "Polymorphic variants in SLC6A4, MAOA, DRD4, and DRD2 have shown statistical associations with major depressive disorder, anti-social behaviour, schizophrenia, and bipolar disorder." (PMID 33809805, 2021). "In a group of 26 women reporting a history of child sexual abuse, symptoms of antisocial personality disorder, depression and substance abuse were more prevalent and methylation of the CpG island surrounding exon 1 of SLC6A4 was increased." (PMID 34377567, 2021). "The eight CpG sites assessed in this study were selected from a region of the SLC6A4 CpG island previously investigated in individuals with major depressive disorder and ADHD." (PMID 33445578, 2021). "This study aims to estimate the contribution of 11 polymorphisms in the genes SLC6A4 (5HTT), HTR1A, HTR2A, HTR1B, SLC6A3 (DAT1), DRD4, DRD2, COMT, and BDNF to suicidal behavior and severity of symptoms of depression and anxiety in the Russian population." (PMID 34199792, 2021). "Last, we wanted to examine which factors (sex, SLEs, primary emotions, 5-HTTLPR genotype and SLC6A4 methylation) or interactions of factors predict age at depression onset." (PMID 33765975, 2021). "In the present study, we examined the role of SLEs, primary emotions, DNA-methylation of SLC6A4 and depression severity for depression onset." (PMID 33765975, 2021). "This review has a particular emphasis on the interaction between early-life social stress and genetic variation of serotonin associate genes including the serotonin transporter gene (5-HTT; also known as SLC6A4), which are key molecules involved in depression." (PMID 33584798, 2020). "All longitudinal studies in this review and studies with more comprehensive considerations of lab and statistical work have consistently found that depression patients had SLC6A4 hypermethylation compared to controls." (PMID 30718449, 2019). "In mother–child pairs that were concordant for depression, increased methylation of the SLC6A4 promoter was seen in both mother and child." (PMID 31019524, 2019). "Several studies have examined associations between peripheral DNA methylation patterns of the serotonin transporter gene (SLC6A4) promoter and symptoms of depression and anxiety." (PMID 30089832, 2018). "Our study of 302 participants is larger than all previous studies investigating SLC6A4 methylation and genetic variation in depression." (PMID 30180828, 2018).
depression (continued). "Moreover, SLC6A4 is significantly related with both increased depressive symptoms and elevated IL-6 plasma levels suggesting that common phathophysiological processes may be associated with depression and inflammation." (PMID 30127739, 2018). "Disrupted serotonergic signaling is often a feature of depression and the role of the serotonin transporter gene (SLC6A4), responsible for serotonin re-uptake, has received much attention in this regard." (PMID 30180828, 2018). "Only the rs3794808 SNP from the 5 SLC6A4 gene polymorphisms (rs3794808; rs140701; rs140700; rs2020939; rs2020936) was considered significantly associated with HADS depression score in patients with COPD (p = 0.022)." (PMID 29927965, 2018). "We focused primarily on SERT (encoded by SLC6A4) because its antagonists include SSRI, highly selective and safe drugs that are widely used to treat depression and other mood disorders." (PMID 28404880, 2017). "Our results provide further evidence for the involvement of SLC6A4 rs4795541 and HTR2A rs6311 polymorphisms in the pathophysiology of depressive disorders in IBS patients." (PMID 28951738, 2017). "Differential methylation of SLC6A4 was previously shown to be independently associated with child abuse, low SES, stress-related depression and increased reactivity of the amygdala to fearful stimuli." (PMID 27869483, 2016). "A recent study has identified predictive links between low SES, differential methylation of the SLC6A4 serotonin transporter gene promoter, elevated amygdala function and symptoms of depression." (PMID 27869483, 2016). "Secondary aims of the study were to examine the association between demographic and (sub)clinical characteristics of depression and between DNA methylation at the SLC6A4 promoter." (PMID 25781010, 2015). "Among genes involved in anxiety and depression, the gene which has received most attention is probably the serotonin transporter (SLC6A4 previously 5-HTT)." (PMID 26175754, 2015). "In combination with exposure to ELS events, both SLC6A4 and BDNF polymorphisms have been attributed to increased risk for depression in later life." (PMID 26583053, 2015). "One of the most investigated genetic polymorphisms regarding gene-by-environment interaction (GxE) and depression is 5-HTTLPR, a functional polymorphism in the upstream regulatory region of the serotonin transporter gene (5-HTT, SLC6A4)." (PMID 25747798, 2015). "Previous studies have shown effects of early life adversity on overall higher methylation in SLC6A4 promoter in adults who were adopted in infancy and in patients with major depression and bipolar disorder." (PMID 25520635, 2014). "In this report, we examined the putative interaction of a set of 12 psychosocial adversities experienced during childhood in relation to the candidate genes BDNF and SLC6A4 on their impact on major depression in adolescence." (PMID 24683520, 2014). "Recent research has provided important insights into the role of genetic variation in the SLC6A4-linked polymorphic region (5-HTTLPR) on neural systems subserving anxiety and depression." (PMID 24286069, 2013). "Another focus of considerable interest and controversy in the field of gene-environment actions is the link between the serotonin transporter gene (5HTT, SLC6A4), stress and the BDNF gene in the risk of depression." (PMID 23503168, 2013). "Further studies on the potential roles of the SLC6A4 gene variations and the depression in survival of colorectal cancer patients are therefore warranted." (PMID 22911682, 2012). "These previously reported findings suggest that multiple variations within the SLC6A4 gene are likely to be involved in altering gene function with adverse consequences for stress response and depression." (PMID 22911682, 2012). "Susceptibility to depression or anxiety has been linked to several genes, including, SLC6A4, which codes for the serotonin transporter protein (also known as 5-HTT and SERT)." (PMID 22911682, 2012).
depression (continued). "Serotonin transporter (SLC6A4) and serotonin receptor (HTR1A, the 13rd) genes are among the strongest candidates underlying the etiology of depression." (PMID 21494644, 2011). "A statistically significant difference in genotype frequency for the SLC6A4 intron 2 VNTR was detected between the subjects with a history of depression and controls (p = 0.004)." (PMID 16822313, 2006). "Epigenetic changes have been well-established in BDNF, COMT, FKBP5, NR3C1, SLC6A4, and DRD2, genes associated with psychiatric disorders, including schizophrenia, major depressive disorder (MDD), bipolar disorder (BP), post-traumatic stress disorder (PTSD), and autism spectrum disorder (ASD)." (PMID 41234420, 2025). "In depression-related models, reduced acetylation at sites such as H3K9ac and H4K12ac has been associated with decreased expression of key mood-regulating genes, including brain-derived neurotrophic factor (BDNF) and the serotonin transporter (SLC6A4)." (PMID 41589304, 2025). "Collectively, these findings illustrate how SLC6A4 dysfunction links epilepsy and depression." (PMID 40941042, 2025). "In depression, altered epigenetic patterns have been observed in key genes related to neurodevelopment and neurotransmission, including the serotonin transporter gene (SLC6A4) and brain-derived neurotrophic factor (BDNF)." (PMID 41589304, 2025). "The aim of this study was to analyze the impact of polymorphisms within the promoters of the MAO-A and the 5-HTT (SLC6A4) genes on the severity of anxiety and depressive disorder symptoms, and adaptation to the disease in patients with reproductive tract cancer." (PMID 40416692, 2025). "For example, the Slc6a4 knockout rat exhibits anxiety and depression-like behaviors alongside altered DNA methylation in the urocortin promoter, while the Nr3c1 knockout mutant reveals sex-specific deficits in fear memory acquisition and extinction, paralleling coping behaviors during stress." (PMID 39728686, 2024). "A role of SLC6A4 in gene-by-environment interaction was initially described by Caspi and colleagues, reporting that 5-HTTLPR s-carriers, who had lower SLC6A4 expression, were more vulnerable to stress in terms of developing depressive episodes when experiencing stressful life events." (PMID 38802956, 2024). "For instance, mutations in genes such as SLC6A4 and HTR1A may lead to abnormalities in the 5-HT system, increasing the risk of depression, anxiety, and other mental disorders." (PMID 39769209, 2024). "Notably, the methylation patterns in blood for the SLC6A4 (solute carrier family 6 member 4) gene correlate with the likelihood of stroke recurrence, post-stroke depression, and decline in neurological function." (PMID 40789569, 2024). "Third, this study did not include controversial risk genes for depression, such as SLC6A4 and 5-HTTLPR; therefore, further investigations are needed." (PMID 36698099, 2023). "Methylation analyses of 9 promoter/regulatory regions of genes known to be implicated in depression/PTSD (ADCYAP1, BDNF, CRHR1, DRD2, IGF2, LSD1/KDM1A, NR3C1, OXTR, SLC6A4) were performed on DNA from blood samples by the MassARRAY EpiTYPER platform, with MassCleave settings." (PMID 36001138, 2023). "Moreover, CMS induced decreased expression of others miRNAs (miR-16-5p, miR-129-5p, and miR-219a-5p), which target Slc6a4, Htr2a, Bdnf, Grm7, Camk2a, and Camk2g genes, which are also related to depression physiopathology and antidepressant response." (PMID 37520658, 2023). "Among a cohort of 17–18 year old students (N = 1482), there was a significant association between the promoter length polymorphism 5HTTLPR (chromosome 17q11, gene SLC6A4) and depression among females, but not in the cohort as a whole." (PMID 36741030, 2022). "In conclusion, numerous investigations have found a link between SLC6A4 methylation and depression." (PMID 36583185, 2022).
depression (continued). "The patient’s SLC6A4 genotype (S/S) may likely explain why switching to fluoxetine proved ineffective and even led to an acute exacerbation of the depression." (PMID 35911243, 2022). "Methylation of SLC6A4 was positively associated with depression severity in women but not with depression severity and age of onset." (PMID 35865627, 2022). "The majority of them demonstrated an increase in SLC6A4 DNA methylation in depressive disorders." (PMID 36583185, 2022). "In addition, we wanted to explore possible sex differences between SLEs, primary emotions, age at depression onset, SLC6A4 methylation and depression severity." (PMID 33765975, 2021). "Additionally, candidate gene studies discovered that BDNF and SLC6A4 hypermethylation were related to depression or major depressive disorder (MDD)." (PMID 34341332, 2021). "There are, however, also studies reporting negative associations between SLC6A4 methylation and depression severity." (PMID 33765975, 2021). "Therefore, sex by genotype interactions should be explored when investigating SLC6A4 methylation in depression." (PMID 33765975, 2021). "In a smaller study of 69 Irish individuals, 30 of whom had a diagnosis of MDD, childhood trauma (specifically physical abuse), but not depression, was significantly associated with SLC6A4 methylation." (PMID 34377567, 2021). "Moreover, hypermethylation of the SLC6A4 promoter region has been correlated with low levels of SLC6A4 expression in psychiatric disorders such as alcoholism, and depression." (PMID 33923526, 2021). "Thus, we wanted to examine the relation of SLEs, primary emotions, DNA-methylation of SLC6A4 and their interactions to age at depression onset in a sample of inpatients suffering from MDD." (PMID 33765975, 2021). "Additionally, several studies have demonstrated an increase in DNA methylation of SLC6A4 in depression." (PMID 33815064, 2021). "Nevertheless, meta-analyses and modern research studies with large sample size did not support the hypothesis of the interaction impact of the 5-HTTLPR genotype within the SLC6A4 gene in the evolution of depression symptoms." (PMID 33784353, 2021). "There might be moderating factors other than sex and 5-HTTLPR that make it difficult to understand the exact function of SLC6A4 in the development and maintenance of depression." (PMID 33765975, 2021). "However, a majority of recent evidence demonstrates an increase in DNA methylation of SLC6A4 in patients with depressive disorders." (PMID 33804455, 2021). "We analyzed the relationship between the severity of depression according to the BDI and the frequency of the genotypes of the 44-bp VNTR polymorphism in the 5-HTT gene (SLC6A4) promoter region and the 30-bp VNTR polymorphism in the MAO-A gene (MAOA) promoter region." (PMID 33379297, 2020). "By analyzing associations of the SLC6A4 polymorphisms with depression, intellectual impairment, tremor and rigidity, we demonstrate in a currently largest PD cohort that 5-HTTLPR is linked with PD depression and rs25531 is associated with rest tremor." (PMID 31024427, 2019). "For example, in an analysis of individuals with MDD, those who had a family member with depression showed a higher percentage of SLC6A4 methylation, indicating that epigenetic regulation of this loci may be related to depression heritability." (PMID 31019524, 2019). "However, different SNPS of the SLC6A4 gene and other genes such as THSD4, CHRNA, CYP2A6 have also been associated with depression in COPD." (PMID 29927965, 2018). "As such, our study may provide support for SLC6A4 methylation as a biomarker of depression, indicating that such a biomarker would need to consider SLC6A4 methylation in combination with genetic variation." (PMID 30180828, 2018).
depression (continued). "Our study investigated the relationship between SLC6A4 promoter methylation and six polymorphisms (5-HTTLPR, rs140700, rs42151417, rs6354, rs25528, rs25531), plus a combined variant (5-HTTLPR/rs25531) independently and in the context of late-life depression." (PMID 30180828, 2018). "The observation of an association between SLC6A4 methylation and neural processing of negative stimuli in the absence of an association with anxiety- or depression-related symptoms is consistent with studies that include healthy individuals (e.g., 16)." (PMID 30089832, 2018). "As reported with high SLC6A4 methylation, the S allele of the 5-HTTLPR genotype leads to decreased gene expression, and has been repeatedly associated with an increased vulnerability for stress-related psychiatric disorders, such as depression and anxiety." (PMID 26401310, 2015). "Given the previously reported functionality of SLC6A4 methylation and the importance of the serotonin transporter (5-HTT) in depression, higher methylation levels during early life may contribute to the increased risk for depression observed among females." (PMID 26401310, 2015). "Furthermore, numerous studies have demonstrated methylation differences in SLC6A4 in individuals with depressive symptoms, depression, and a history of early life stress." (PMID 26401310, 2015). "Additionally, epigenetic changes such as decreased DNA methylation of the SLC6A4 promoter in patients with depression and epilepsy may increase serotonin transporter levels, potentially worsening mood symptoms." (PMID 40941042, 2025). "This polymorphism in the SLC6A4 gene promoter region, particularly the 5-Hydroxytryptamine transporter linked polymorphic region (5-HTTLPR), along with related SNPs, has a significant impact on susceptibility to depression and other psychiatric disorders, as well as treatment response." (PMID 40342516, 2025). "However, how chronic stress may affect SLC6A4 gene expression in PD depression remains to be explored." (PMID 37374342, 2023). "We wanted to determine whether epigenetic changes, such as DNA methylation patterns of the candidate genes (BDNF, COMT, and SLC6A4) in peripheral blood, correlate with the duration and acute severity of anxiety and depression symptoms measured with clinical scales (BDI-II, HAM-A, and IDS-C)." (PMID 37754245, 2023). "Epigenetic modifications in the promoter of the SLC6A4 gene might constitute a specific biological mechanism through which adversity contributes to an altered brain function, which, in turn, moderates the emergence of depression." (PMID 34590201, 2023). "Interestingly, SLC6A4 and SLC6A15 gene variants have been associated with age at depression onset." (PMID 36557240, 2022). "Despite this lack of specific data on SLC22A2 variants on the risk of depressive disorders, gene-diseases association biobanks suggest they may have the second highest association strength (after SLC6A4)." (PMID 36557240, 2022). "However, there could still be differences in SLC6A4 methylation when comparing inpatients suffering from depression to healthy controls." (PMID 33765975, 2021). "Depending on the specific CpG site or cluster of CpG sites examined, there may be positive or negative associations between SLC6A4 methylation, personality and depression." (PMID 33765975, 2021). "Recently, extensive works of literature have investigated the relationships between 5-HTTLPR and depression, the serotonin transporter gene-linked promoter region (5-HTTLPR) is a variable number tandem repeats (VNTR) located in the promoter region of SLC6A4 (the human 5-HTT-encoding gene)." (PMID 33193645, 2020). "Antidepressants that block the serotonin transporter, (Slc6a4/SERT), selective serotonin reuptake inhibitors (SSRIs) improve mood in adults but have paradoxical long-term effects when administered during perinatal periods, increasing the risk to develop anxiety and depression." (PMID 30279456, 2019).